CD38 (CD38 molecule)
Diseases named in the same sentence as CD38 in open-access papers (continued):
Sharing a sentence is not in itself a finding about the gene and the disease.
infection (continued). "Interestingly, CD38/HLA-DR coexpression on TIGIT+NK cell population was higher than the TIGIT−NK cell population in HIV-1-infected individuals who were at different phases of infection and in HIV-1-negative donors (all P < 0.05)." (PMID 33717085, 2021). "Consistently, in the monocentric cohort of 706 patients reported by Visentin and colleagues, major infections–defined as events requiring in patient management or intravenous antibiotics–were associated with clinical stage, IGHV mutational status, high-risk cytogenetics and CD38 positivity." (PMID 34359757, 2021). "Indeed, lethal infection with MRSA upregulated the production of IL-6, TNF-α, and MCP-1 in the circulation and organs such as the liver, lungs, and kidneys, which was correlated with the induction of CD38 associated with pro-inflammatory macrophages." (PMID 34681611, 2021). "Taken together, reactivation of HSV-1 in the later phase of SARS-CoV-2- infection occurs in parallel with a drop of antiviral innate responsiveness as shown by decreased expression of Interferon-stimulated genes and a concurrent increase of highly activated CD38+HLADR+ CD8 T cells." (PMID 34197543, 2021). "However, whether manipulation of specific CD38 activities represents an adequate strategy for host-directed therapy against infections requires further investigation." (PMID 31963337, 2020). "Furthermore, in HIV-infected individuals failing to control infection, the co-expression of CD38 and PD-1 on CD4+ and CD8+ T cells could be a sign of T-cell activation." (PMID 32876566, 2020). "Although the receptorial function of CD38 toward CD31 was shown to facilitate human T cell adhesion to endothelial cells, and it could be responsible for weak leukocyte binding to the endothelium, a role for CD38 in recruitment of effector T cells to sites of infection remains elusive." (PMID 31963337, 2020). "In conclusion, despite considerable knowledge existing on the diverse roles of CD38 in the immune response, new (and more sophisticated) approaches are required in order to determine the consequences of targeting specific CD38-mediated activities during the host response to infection." (PMID 31963337, 2020). "To determine the cytotoxic potential of CD38+ CD8+ T cells generated during P. vivax infection, we measured their intracellular expression of granzyme B and perforin by flow cytometry, in an independent cohort (n = 2 because of logistics associated with vivax experimental infection)." (PMID 27930660, 2016). "Thus, we speculate that the function of our novel population of CD38+ CD4+ T cells during infection might be to control and restrain the immune response, rather than to promote it." (PMID 27662621, 2016). "Thus, CD38+ CD4+ T cells were associated with a ‘naïve-like’ effector T cell phenotype (CD45RA+Ki67+Bcl2low), and the proportion of cells expressing each marker was significantly affected upon infection within this cell subset." (PMID 27662621, 2016). "By day 17 post-infection, the CD19+ B cell population, along with the assayed markers, including CD38, PD-L1, Ki-67, and IRF4 within this population, was significantly higher in PBMCs depleted of CD4+ T cells compared with intact PBMCs." (PMID 40733503, 2025). "Inhibition of CD38 with Ab68 effectively prevented infection-induced NAD+ depletion, supporting the notion that CD38 is the main driver of this process in the brains of ZIKV-infected mice." (PMID 41362627, 2025). "Effector CD4+ T cells in the brains of the SFV‐only and SFV + IAV–coinfected groups displayed similar activation phenotype of CD38+ PD1+, KLRG1+ compared with IAV‐only infection." (PMID 39971320, 2025). "In this study, we observed abnormal high CD38 protein levels and low NAD+ levels in old murine BMMs after infection with oral pathogens compared to young controls." (PMID 40649955, 2025). "CD38, a nicotinamide adenine dinucleotide (NAD+) glycohydrolase, increases in old murine macrophages after infection compared to young controls." (PMID 40649955, 2025).
infection (continued). "Conversely, at 10 dpi, most tetramer+CD8+ T cells in the spleen of SFV + IAV animals had higher activation status compared with IAV‐only infection, expressing activation markers CD25+ CD38+PD‐1+, CD25+CD38+, CD25+PD‐1+ and CD38+." (PMID 39971320, 2025). "This revealed a decrease in CD8+ T cells coexpressing various combinations of activation markers CD38, Ox40, and ICOS following breakthrough infection, but again only in the context of pregnancy." (PMID 40693463, 2025). "By contrast, in IAV‐only infection, a higher proportion of tetramer+CD8+ T cells had CD38+PD‐1+, CD25+CD38+PD‐1+ and KLRG1+ phenotypes." (PMID 39971320, 2025). "In‐depth analysis revealed that the expression of CD38+PD‐1+ was higher, while KLRG1+ expression was lower on KbE1159+CD8+ T cells in SFV + IAV–infected brain in comparison to SFV‐only infection." (PMID 39971320, 2025). "To investigate the activation profiles at these late stages post-infection or post-vaccination, we compared the percentage of CD8+CD38+ and HLA-DR+ T cells among the groups." (PMID 40573882, 2025). "Antibody-based immunotherapies targeting the malignant plasma cell-specific antigens CD38, CD138, BCMA, FcRH5, and GPRC5D have demonstrated a safety profile, with mainly low-grade cytokine release syndrome, cytopenias, and infections." (PMID 39025844, 2024). "Further, it has recently been shown that CD38 and CXCR6 expression defines Trm cells in multiple organs and during different types of infection." (PMID 39392861, 2024). "In the liver, where CD38 expression marks the tissue-resident viral-specific CD8+ T cells, a lesser distinction between the different infection types was observed." (PMID 38954588, 2024). "CD38, a nicotinamide adenine dinucleotide (NAD+) glycohydrolase, increases during infection or inflammation." (PMID 39682719, 2024). "We found that the CD103+CD49a+ population is maintained as a long-term CD69+CD38+CXCR6+ Trm subset in the liver, which showed rapid expansion and cytokine production after secondary infection." (PMID 39392861, 2024). "We found that the frequencies of HLA-DR+CD38+CD4+ and HLA-DR+CD38+CD8+ T cells were higher in PLWH post-breakthrough infection than in those who were pre-infected." (PMID 38140668, 2023). "A Th1 response is also consistent with increased frequency of activated monocytes expressing CD38 and activated/memory CD8 cells in BM, which we find particularly evident after infection with Hz-restricted parasites." (PMID 37539049, 2023). "In order to characterize in detail the cytotoxic T cell response during incubation as well as early and late acute infection phases, CD8+ cells were analyzed for their activation (CD25, CD38), exhaustion (PD-1) and differentiation status (CD45RA, CD27, CD127)." (PMID 35215797, 2022). "In agreement with the CCR5-tropic transduction of CD34+CD38+ progenitors in vitro in our study, both X4 and R5 HIV-1 appear to target HSPCs, whereby R5 infection/transduction is restricted to less immature progenitors." (PMID 36230931, 2022). "Accordingly, studies using humanized mice observed infection of CD34+CD38+ progenitors by HIV-1 strains of all tropisms, including CCR5-tropic strains, albeit at much lower infection rates than by CXCR4-tropic or dual-tropic strains." (PMID 36230931, 2022). "As an extracellular enzyme or intracellular enzyme, CD38 promotes the metabolic collapse of pathogens by degrading NAD+ and its precursors, thus limiting the development or progress of infection." (PMID 35251964, 2022). "This analysis showed that a rapid decline of TEX, T-bet+, and CD38+ subsets in CH, while TEFF increased over the course of infection." (PMID 36477661, 2022). "An increase in CD38+ immune cells is reported in HIV infections, likewise in infections with Epstein–Barr virus and cytomegalovirus." (PMID 36077708, 2022).
infection (continued). "Polyfunctionality of these cells in regard to major Th1 cytokine production (MIP-1β, IFN-γ, IL-2) and expression of activation/proliferation markers, i.e., CD69, CD38, CD25, and Ki67, suggest a potential central role in the control of infection." (PMID 34283810, 2021). "Upon MCMV-GP33 infection, two TRM cell clusters expressing CD38, CD11a, CD11c, CXCR6, and Sca-1, typified by divergent KLRG1 expression, connected uniquely to the liver." (PMID 33458613, 2021). "Infection by several viruses, including HIV-1, and by bacteria, is known to trigger CD38 expression." (PMID 34871367, 2021). "Among the varied consequences of increased CD38 expression, the implications of a substantial decline in NAD+ levels on the inflammatory response and the outcome on the course of infection offer an open area for exploration." (PMID 31963337, 2020). "A decade later, this molecule drew attention after Edward Chini and colleagues unearthed the role of CD38 as a major NAD+ catabolizing enzyme having a number of pathophysiological implications in aging, infection, and tumorigenesis." (PMID 32709019, 2020). "We isolated primary human B lymphocytes from adenoid tissue and sorted the fraction of quiescent naive B cells (IgD+/IgH+, CD38−, CD27−) for our infection experiments." (PMID 31530670, 2019). "During the acute phase of the infection, increased expression of CD69, CD38, Ki67, and granzyme B was observed on NK cells indicating activation." (PMID 31156653, 2019). "Upon pathogen infection, these BAM transform into CD27+CD38+CD138+ PCs that will produce large amounts of antibodies, particularly IgG or IgA." (PMID 29312291, 2017). "The co-expression of CD62L and CD38 in NK cells was also pronounced in HIV-1-infected individuals, suggesting that even immature NK cells can display an activated profile during infection." (PMID 28373665, 2017). "CD38+ CD4+ T cells retained their cytotoxic function and impaired ability to produce cytokines throughout infection." (PMID 27662621, 2016). "Both the absolute numbers of CD38+ in CD4+ T cells and relative frequency of CD38+ versus CD38- CD4+ T cell were increased upon infection." (PMID 27662621, 2016). "Thus, we speculate that the analysis of epigenetic modifications to cytokine promoters in circulating CD38+ CD4+ T cells in the context of natural or experimental infection will inform the molecular mechanisms controlling cytokine production within this cell population." (PMID 27662621, 2016). "MAIT cells were readily and specifically activated in response to DENV-treated APCs (multiplicity of infection (MOI)=1), as indicated by production of IFN-γ and Granzyme B, as well as, expression of CD38, with minimal production of TNF-α." (PMID 27337592, 2016). "Conversely, the expression of the anti-apoptotic marker Bcl2 was significantly reduced in CD38+ CD4+ T cells compared to CD38- CD4+ T cells both prior to and at peak infection (p = 0.002)." (PMID 27662621, 2016). "In both patients, the frequency of CD38-expressing CD8 T-cells (black triangles) was low in the first days after infection, and then increased, reaching the highest frequency at T13 for pt1 (79.6%) and at T8 for pt2 (79.5%), declining thereafter." (PMID 27031961, 2016). "Analysis of CD38 revealed marked in vivo activation of MAIT cells, which increased over the course of infection and peaked at a critical moment for DENV infected patients—the day of defervescence." (PMID 27337592, 2016). "Unexpectedly, IFN-γ production was significantly impaired in the CD38+ CD4+ T cell subset both prior to and during infection (p = 0.031 and p = 0.031)." (PMID 27662621, 2016). "The expression of Ki67 was significantly increased in CD38+ CD4+ T cells compared to CD38- CD4+ T cells prior to and during infection (p < 0.0001)." (PMID 27662621, 2016).
infection (continued). "This heterogeneity is somewhat similar to results obtained by a study of human T cells, where, seven days after infection, a strong variation in the frequency of CD4+CD38+Ki-67+ and CD8+CD38+Ki-67+ T cells was observed between different individuals." (PMID 25971313, 2015). "An expansion of CD38+ CD69+ T cells in the acute phase compared to the resolving phase of infection with an increased in mRNA expression of IFN-gamma, TNF-α and IL-4 has reflected an increment in CD3+ CD38+ CD69+ T cells." (PMID 24963498, 2014). "Infection also induced the expression of co-stimulatory molecules such CD40, CD83, CD86, adhesion molecules (CD38, Itga5, and ICAM1), and tissue invasion molecules such as MMP12 and MMP14." (PMID 22928052, 2012). "In this setting, the activated HIV-specific CD4+ T cell, expressing CCR5 and high levels of CD38, are prime targets for infection in vivo during primary HIV-infection, which explains the preferential infection of HIV-1 specific CD4+ T cells." (PMID 19165342, 2009). "Immunologically, the infection group showed significantly elevated levels of nCD64 (45.39 vs. 11.16, p < 0.05) and enhanced CD8+ T cell activation, particularly CD8+CD38+ T cells (81.54% vs. 66.89%, p < 0.05)." (PMID 41988203, 2026). "In lungs, however, prior IAV infection elicited effector CD8+ T cells with highly activated CD38 and/or CD25 phenotypes, while SFV-only infection elicited distinct effector CD8+ T cells with increased frequencies of KLRG1 expression, a hallmark of short-lived effector T cells." (PMID 39817772, 2025). "Although we showed that old murine BMMs displayed higher CD38 protein levels after infection with the oral pathogens Aa or Pg, it was not clear which mechanisms were associated with the increase in CD38 in old murine BMMs." (PMID 40649955, 2025). "Coexpression of CD38 and PD‐1 on CD8+ T cells of SFV + IAV mice may also suggest hyperactivation of T cell because of the need to control infections from two invading pathogens." (PMID 39971320, 2025). "In addition, another potentially regulatory T cell subset, CD38+CD27+DN T cells, expanded at week 8–9, after the first infection, as in the previous single-sex 1x CHI13." (PMID 40707512, 2025). "Similarly, at week 9 and 26 a CD38+CD27+ DN T cells increased significantly in the reinfection (all) group, as well as week 26 in the infection control group." (PMID 40707512, 2025). "First, we compared CD38 protein levels in young vs. old murine BMMs with or without infection with the oral pathogens Aa or Pg." (PMID 40649955, 2025). "Consequently, plotting mean scaled expression of CD38 and TNF in infection-induced expanded clusters against age revealed significant correlations." (PMID 40834853, 2025). "Consistently, we observed that patients with positive IgA, IgG and IgM responses on day 1 of infection displayed high frequencies of HLA-DR+CD38+ CD4+ T cells compared to HIV-1 negative individuals, but not significant." (PMID 40607402, 2025). "We focused our analysis on CD69-, CD38-, CD25-, and HLA-DR-expressing CD4 T cells, along with CD69- and CD38-expressing CD8 T cells, whose frequency increased consistently across all donors upon infection with at least one strain (compared to the uninfected control)." (PMID 40162896, 2025). "It remains unclear how differences between CD38 antibodies affect their pharmacodynamic utility, efficacy, and safety in AMR, including risks of infection, malignancy, or TCMR." (PMID 40444214, 2025). "Future studies should determine if old murine BMMs could enhance CD38 levels and reduce NAD+ levels after infection with other oral pathogens." (PMID 40649955, 2025). "Patients in Endotype3 showed the increased expression of IFN-gamma and the highest percentage of CD8+CD38+ cells and CD8+HLA-DR+ cells, which might be the complicated results of interactions between infection and primary disease." (PMID 38533498, 2024).
infection (continued). "CD38 expression on CMV-specific CD8+ T cells was enriched in secondary lymphoid tissues, i.e., spleen and bone marrow, and even reached higher levels in the spleen compared with the viral-specific T cells elicited after chronic LCMV-clone 13 infection." (PMID 38954588, 2024). "CD38 was found to be essential during cytoskeleton rearrangements in phagocytes, the NAD+-dependent bacterial engulfment, and ADPR-dependent signaling needed for immune cells’ migration to the infection site." (PMID 36675642, 2023). "It occurs in parallel with increases in CD38+, HLADR+ and CD8 T-cells and decreased expression of interferon-stimulated genes; in other words, with dysregulation of the patient’s immune response produced by the primary infection." (PMID 36674947, 2023). "Similarly, the frequency of CD38+Ly6C+ tissue-resident monocytes and to a better extent than of CD38+Ly6Chigh pro-inflammatory monocytes was reduced after AAV-LAV-BPIFB4 infection, as compared to those of AAV-GFP-aged mice." (PMID 35087020, 2022). "In children, no changes in CD38/HLA-DR co-expression on CD4+ T cells were found between different time points after infection." (PMID 35197982, 2022). "In severe/critical patients there was a greater proportion of intermediate and non-classical monocyte subsets expressing CD38 compared both to pre-infection samples and to mild/moderate patients, likely reflecting enhanced activation." (PMID 36522333, 2022). "Taken together, our results suggest that the expression of the T cell activation marker CD38 solely warrant the infection status and is not quantitatively induced by the presence of live mycobacteria during TB." (PMID 35492319, 2022). "CD38 is required in TFEB (transcription factor for EB, the primary transcription factor involved in regulating the expression of lysosomal elements) activation by ROS (reactive oxygen species) during infection." (PMID 36077708, 2022). "One was that CD14, CD38, and ABCA1 expression identify macrophages that are prone to infection." (PMID 32544188, 2020). "PHA, irrespective of infection status, maintained elevated levels of the activation phenotypes CD38+HLA-DR+ and CD38+HLA-DR- (p ≤ 0.0001) compared to the unstimulated infected control." (PMID 31396221, 2019). "A similar pattern of activation marker expression was seen for CD69 as well as for CD38, the latter depicted as median fluorescence intensity (MFI), albeit with lower percentages of CD69 expression on CD56bright NK cells during the acute phase of infection." (PMID 31467285, 2019). "Neutrophils lacking CD38 demonstrate altered mobilization from the bone marrow and migration to sites of infection." (PMID 31214171, 2019). "Uninfected BMDM did not appreciably express CD38 or Egr2, markers of classically (M1) and alternatively (M2) activated macrophages, respectively, nor did infection change the lack of polarization." (PMID 28278296, 2017). "Consistent with this is our observation that there were no changes in the cytotoxic phenotype of circulating CD38+ CD4+ T cells were observed in the volunteers following infection." (PMID 27662621, 2016). "Thus, we examined the cytolytic potential of CD38+ CD4+ T cells by measuring their intracellular expression of perforin and granzyme B by flow cytometry both prior to and at peak infection." (PMID 27662621, 2016). "There was a higher frequency of CD38+ CD4+ T cells circulating following infection in P. falciparum but not P. vivax infected volunteers." (PMID 27930660, 2016). "The frequency of cells expressing perforin or granzyme B was significantly greater in CD38+ CD4+ T cells than in CD38- CD4+ T cells prior to and post infection (p = 0.001 and p = 0.011 prior to infection, and p = 0.012 and p = 0.017 at peak infection for perforin and granzyme B, respectively)." (PMID 27662621, 2016).